CD4 (CD4 molecule)
Diseases named in the same sentence as CD4 in open-access papers (continued):
Sharing a sentence is not in itself a finding about the gene and the disease.
viral infection (continued). "In the context of infection, it is generally produced by effector CD4 and CD8 T cells, and it acts via STAT3 signaling to downregulate expression of Th1 cytokines and CD4 T-cell activation, but can also have a variety of other diverse roles, especially during viral infection." (PMID 30641955, 2019). "Likewise, the capacity to neutralize post-CD4 engagement has been implicated in blocking cell–cell transmission of HIV-1 where engagement of CD4 is more rapid than in the setting of free virus infection." (PMID 30650070, 2019). "This follicular helper type function may also act to promote a tissue specific antiviral response on CD4 Tfh cells differing from the cytolytic response facilitated by chronic viral infection reservoirs in secondary lymphoid organs." (PMID 31275308, 2019). "Depletion of microglia changes the response of CD4+ T cells to viral infection in the brain, the total number and percentage of CD4+ T cells decrease, and the frequency and number of Tregs also decrease, indicating that microglia are crucial for fully activating virus-specific T cells." (PMID 30967139, 2019). "Similarly, CD4 T cells are thought to control viral infection through multiple mechanisms, including enhancement of B and CD8 T cell responses, production of inflammatory and anti-viral cytokines, cytotoxicity, and promotion of memory responses." (PMID 31552052, 2019). "Collectively, our data suggest that CECs via ROS production upregulate a wide range of genes, and some of them may explain enhanced viral infection/replication in CD4+ T cells." (PMID 31772057, 2019). "Similarly, pDCs express granzyme B, which mediates killing of CD4 T cell during viral infections like HIV." (PMID 31181776, 2019). "In contrast, while CD4+IFN-γ+ responses were greater following KOS infection than D22 (ICP22 null) virus infection on day 14 PI (61.7% vs. 23.2%, P < 0.001), the differences between these viruses were not statistically significant on day 28 PI (35.6% vs. 27.5%, P > 0.05)." (PMID 31387116, 2019). "Besides, CD4 and CD8 double positive T cells (CD4+CD8+ T cells) are important cell phenotypes during viral infection." (PMID 31551984, 2019). "It has been shown that developing virus-specific CD8+ and CD4+T cells necessitates long-term protection from persistent viral infection besides the natural killer (NK) cells that are capable of identifying viral Ags in association with either class I or class II MHC molecules." (PMID 31739735, 2019). "Adjuvant effects following IL-2 administration observed during systemic viral infection support that memory CD4 T cell-derived IL-2 may have similar proinflammatory effects in this setting." (PMID 31412088, 2019). "CD4+ T cells are necessary for protective immune response after virus infection." (PMID 31757053, 2019). "The acute wave of activated EBV-specific CD4-CTLs in primary infection markedly contrasts with classically reported CD4-CTLs, which have long been considered a feature of viral persistence and terminal differentiation in the setting of other viral infections." (PMID 31308093, 2019). "The nature of CD4 T cell help changes over the course of persistent viral infections." (PMID 30372487, 2018). "Importantly, both ligases are expressed in CD4+ T cells, underscoring that they can regulate Tat activity during normal viral infection of target immune cells." (PMID 29845934, 2018). "A differential dependence of CD4 T cell help on development of virus-specific CD8 TRM in different viral systems may depend on the type of viral infection." (PMID 30372487, 2018). "Moreover HIV infection causes a poor immune function due to CD4+ T-cells infection, and both HIV and HCV infections promote an immune response to try to control both viral infections." (PMID 30400258, 2018). "Finally, CD4 T cell mediated immuno-inflammatory responses to a virus infection were similar between WT and HK2 KO animals." (PMID 29352298, 2018).
viral infection (continued). "However, the molecular components that modulate CD4 T cell functions in response to viral infection or vaccine are incompletely understood." (PMID 29734372, 2018). "Furthermore, it has been demonstrated in humans that the presence of memory cross-reactive CD4 or CD8 T cells is correlated with cross-protection against A(H1N1)pdm09 or A(H7N9) virus infection." (PMID 30356772, 2018). "Similarly, in mice vaccinated with the yellow fever vaccine, transfer of CD4 T‐cells and immune serum provide the most optimal immune protection." (PMID 29570776, 2018). "To determine if direct viral infection could explain the activation, we measured CD4 expression on Vδ1+ cells." (PMID 30405182, 2018). "Thus, understanding the molecular mechanisms governing CD4 T cell responses through either TCR-dependent or cytokine-dependent signals can yield insight into host protection against viral infection or protective antibodies induced by vaccines." (PMID 29734372, 2018). "Interestingly, TFH cells accumulate during the persistent phase of viral infections with non- or poorly cytopathic viruses while differentiation of naïve CD4 T cells into Th1 CD4 T cells is largely abrogated in this phase due to a sustained IFN-I environment." (PMID 29887868, 2018). "Similarly, a rare population of CD4+ cytotoxic T cells was previously identified in the patients with chronic viral infection of CMV." (PMID 29599759, 2018). "Cytotoxic CD4 T cells are detected in the circulation at much higher levels than previously realized and are now recognized to have an important role in the immune response to viral infections." (PMID 28167943, 2017). "However, we and others have shown that CD4 CTL are also detected in the primary response to acute viral infections, which will be discussed later in this review." (PMID 28167943, 2017). "Overall, our results corroborate the assertions that the BrMΦ QVOA underestimates the size of the virus reservoir and that infection in the brain is highly focal and is not evenly distributed in the tissue such as has been observed in viral infection in CD4+ T cells in the blood." (PMID 28811349, 2017). "We initially evaluated the CD4 T cell responses following peptide immunization alone or in the setting of a prior viral infection to determine if prior viral infection resulted in alterations in the CD4 T cell response magnitude or specificity post-immunization." (PMID 28493882, 2017). "Historically, cytolytic CD8+ T cells have been recognized as the major contributors to the control of acute and chronic viral infections even though, in the last decade, many studies described the presence of activated CD4+ T cells in the peripheral blood of HIV-1-, CMV-, and EBV-infected patients." (PMID 28289418, 2017). "In perspective, therefore, CD4+ cytolytic effectors may become integral part of new therapeutic strategies for viral infections and virus-driven tumors." (PMID 28289418, 2017). "An inversion of the CD4/CD8 ratio in peripheral blood mononuclear cells (PBMCs) has long been associated with acute viral infection because of the large expansion of CD8 T cells, another pathognomic finding in AIM." (PMID 29208744, 2017). "CD4+ T cells represent the major T cell population and are mainly associated with Th1 and Th2 immune responses via cytokine production and antibody secretion, while CD8+ T cells play an important role in protection against viral infections." (PMID 28933754, 2017). "In addition to inducing effector CD4+ T cells, viral infection can have an impact on regulatory T cells (Tregs), a T cell subset that plays a key role in the maintenance of immune homeostasis." (PMID 28231312, 2017). "In addition to CD8 T cells, CD4 T cells also play a crucial role during the development of chronic viral infections." (PMID 28715493, 2017). "The percentages of CD4+ T cells were evaluated 10 weeks after viral infection at study termination." (PMID 28279181, 2017).
viral infection (continued). "While productively infected CD4+ T cells were found throughout the LN tissues, B cell follicles contain 31 times more infected CD4+ T cells than extrafollicular regions, indicating that B cell follicles are the preferred site of viral infection, replication, or both in CD4+ T cells." (PMID 28620380, 2017). "The percent of CD4+ T cells was lower in CerS2-null mouse liver before and after viral infection." (PMID 29163475, 2017). "It was also observed that 41BB-L and OX40-L could trigger CD4 T cell cytotoxic response in viral infections." (PMID 28974950, 2017). "Regardless of whether APC killing is a common function of CD4 CTL during natural viral infection, manipulation of cytolytic CD4 responses may provide interesting new avenues for immunotherapy." (PMID 28167943, 2017). "Therefore, Blimp-1 plays an important role in regulating the effector function of CD4+ T cells during viral infections to maintain T cell homeostasis." (PMID 28732506, 2017). "The role of CD4+CD25+Foxp3+ in acute viral disease is still controversial." (PMID 28265274, 2017). "It is noteworthy that CD4 CTLs have been mostly observed in virus infection models." (PMID 28280496, 2017). "Since virus infection typically leads to a Th1-skewed condition, CD4+ T cells may differentiate into Th1 cells upon exposure of IL-12 or IFNγ produced by APC." (PMID 28280496, 2017). "Here we show that absence of IL-6 reduces EV-A71 lethality, the damage in the CNS, and tissue viral loads with increased levels of CD4 T cells in the spleen and virus-specific neutralizing antibody in the serum in a manner rarely reported in other virus infections." (PMID 29233145, 2017). "To test this hypothesis, we sorted CD4+ T cells from LCMV-infected mice on day 4 because it has been shown that CD69 expression levels are near their peak after virus infection in vivo." (PMID 29250063, 2017). "CD4 T cells with cytotoxic function were once thought to be an artifact due to long-term in vitro cultures but have in more recent years become accepted and reported in the literature in response to a number of viral infections." (PMID 28167943, 2017). "Taken together, the data indicates that αCD137 therapy can induce the exocytosis pathway in cytotoxic CD4+ T cells during a chronic retroviral infection and might therefore be an interesting therapeutic approach to treat chronic viral infections." (PMID 28798348, 2017). "If our speculation holds true, then it will provide a reasonable explanation for the activity of ibalizumab, i.e., the site recognized by ibalizumab on CD4 is a critical site for the full engagement of gp120 with CD4 during viral infection." (PMID 28429756, 2017). "In addition, the percentage of CD4+ T-cells was decreased in livers when compared with the blood in inflammatory liver injuries and viral infections." (PMID 29213216, 2017). "Although the transcriptional signature of dysfunctional CD4+ T cells obtained during chronic viral infection is distinct from that expressed by exhausted CD8+ T cells, exhausted CD4+ and CD8+ T cells also share certain hallmarks that are unique to T cell dysfunction." (PMID 26967901, 2016). "Furthermore, B cell depletion limits the generation of CD4+ memory T cells and reduces protection against disseminating virus infection." (PMID 27558631, 2016). "In this context previous studies have shown that natural virus infection elicits CD4+ T cell responses to many late structural proteins, and that de novo-infected B cells can present such proteins via the HLA class II pathway for recognition by late antigen-specific CD4+ T cell clones." (PMID 27096949, 2016). "T-cell CD4+ receptors are the direct interactors of MHC class II molecules and MHC class II genes have been associated with the outcome of many viral infections such as those caused by HBV, HCV, HIV, EBV and dengue viruses including the severity of WNV disease." (PMID 27812212, 2016).
viral infection (continued). "Physiologic levels of oestrogens stimulate the expansion of CD4+ regulatory T cells, especially during the ovarian follicular phase and these cells play an important role in maintaining immune homeostasis during viral infections." (PMID 26900031, 2016). "The innate immune response differs according to the cell type or cell state, such as activated vs resting CD4+ T cells, and this may in turn affect the outcome of viral infection." (PMID 27350062, 2016). "In addition to the indirect mechanism of killing that CD4 T cells are most known for, there is evidence for “cytotoxic” CD4 T cells, particularly in viral infection models." (PMID 27472363, 2016). "Further studies are needed to determine whether and how the expression of ThPOK and Runx3 dictate the development of cytotoxic CD4 T cells following viral infections as well as the cellular and environmental factors that modulate their expression." (PMID 28003809, 2016). "The ability of CD4 T cells to acquire cytotoxic functions have been mostly attributed to T helper type 1 (Th1) cells after viral infections; however, it is now clear that other CD4 T cell subsets including regulatory T (Treg) cells can also secrete effector molecules and exert cytotoxic effects." (PMID 28003809, 2016). "Because CD4 T helper subsets begin to diverge within the first few days of viral infection and we found fewer Tfh and more Th1 precursor cells in the absence of TGF-β signals during LCMV infection, we questioned when TGF-β was required for Tfh differentiation during influenza virus infection." (PMID 25569154, 2015). "Notably, treatment of FDC cultures with sCD21-Ig reduced viral infection of CD4 T cells significantly (mean±SD 299±134) compared to isotype control treatment (mean±SD, 3656±1261)." (PMID 26623655, 2015). "High PD1 expression is associated with T-cell exhaustion; blockade of the PD1/PD-ligand pathway with antibodies against PD1, PD-L1, or both, augmented or restored the function of viral-infection-specific and tumour-specific CD4+ T cells and CD8+ T cells in mouse and human studies." (PMID 26361042, 2015). "In addition, the long life span of macrophages as compared to the CD4+ T cells make them important viral reservoirs in infected individuals especially in the late stage of viral infection where CD4+ T cells are largely depleted." (PMID 25835530, 2015). "Using SIVmac carrying a mutated Vpx gene with a single amino acid change that prevents it from binding to DCAF1 and subsequently mediating the degradation of SAMHD1, we show that virus infection of CD4+ T lymphocytes is markedly compromised both in vitro and in vivo." (PMID 25996507, 2015). "Given that we proposed that Tat effects on host cell gene expression might be relevant to normal HIV biology we asked whether the TSG and TDG are also modulated in response to viral infection of primary CD4+ T cells." (PMID 26488441, 2015). "Here, we present investigations on Tax-mediated LTR activation in the context of viral infection using HTLV-infected primary CD4+ T cells and the virus-producing T cell line (MT-2) and describe the involvement of myocyte enhancer factor-2 (MEF-2) in this process." (PMID 25809782, 2015). "Thus, our previous data and the current results suggest an interplay of CD4+ helper T cells, Tregs and NK cells also in viral infections with IL-2 being the specific link between these cell populations." (PMID 26220086, 2015). "As SAMHD1 restricts viral infection to a greater extent in naïve CD4+ T cells compared with memory cells, we speculated that it could further reduce double infection of TN cells and drive the observed subset differences between single and double infection." (PMID 26559763, 2015). "On the other hand, virus infection also affects CD4+T-cell responses." (PMID 25836633, 2015). "CD4+ T cells decline faster because of the incapability of CD8+ T cells to control viral infection." (PMID 26709961, 2015).
viral infection (continued). "Thus, under physiological conditions of virus infection in primary CD4+ lymphocytes and in a stable cell line expressing Mamu-A1*002, Mamu-KIR3DL05+ NK cells are specifically impaired in their ability to contain SIV replication." (PMID 26333068, 2015). "CD4+ T cells can act as cytotoxic T cells in certain viral infections, and we hypothesize that CD4+ cytotoxic T cells may be generated in post-exposure VLP-treated mice, at least in the absence of CD8+ T cells." (PMID 25785602, 2015). "However, if the drug efficacy in compartment II is relatively low (e.g. ε2 = 0.4) compared with the high efficacy in compartment I (e.g. ε1 = 0.9), then CD4+ T cells decline even when HAART is initiated at the beginning of viral infection." (PMID 26709961, 2015). "Thus, Treg cells appear to play a central role in effector CD4 T cell fates during viral infection, likely by controlling the local bioavailability of both IL-2 and TGF-β." (PMID 25569154, 2015). "Importantly, retention of transferred SR T cells at slightly declining frequencies within the total CNS CD4 population out to day 30 p.i. negated preferential expansion/survival during chronic viral infection." (PMID 26559484, 2015). "Virus-specific CD4+ T cells play a major role in viral infections, such as hepatitis C virus (HCV)." (PMID 25767470, 2015). "Increased levels of α‐defensins during viral infection could therefore recruit both CD4+ and CD8+ cells to the airways." (PMID 24673807, 2014). "Thus, it is plausible that AhR activation during development can change epigenetic regulatory machinery in CD4+ T cells, leading to intrinsic differences when these cells respond to viral infection." (PMID 25051576, 2014). "Murine Bregs have been shown to modulate APC function and inhibit CD4+ T cell proliferation but to our knowledge this is the first time this has been demonstrated for IL-10-competent Bregs during a human viral infection." (PMID 24739950, 2014). "Similarly, HSV-2 –specific CD4+ T cells have been shown to play a role in resolution of an acute virus infection of the lumbosacral ganglia neurons following genital HSV-1 infection." (PMID 25485971, 2014). "Several recent studies have reported that cytolytic CD4+ T lymphocytes, which may represent a new CD4+ lineage, can contribute to the control of certain viral infections." (PMID 25121947, 2014). "The role of CD4+CD25+Foxp3+ Tregs in acute viral diseases is still debatable." (PMID 25188232, 2014). "We decided to (i) investigate if T/F virus infection is dependent on cell surface CD4 levels (as previous work suggested that the T/F strains are less sensitive to soluble CD4) and (ii) directly measure entry efficiency of full-length T/F viruses in both T cell lines and MDM." (PMID 24656066, 2014). "Moreover, since CD4+CD25+Foxp3+ Treg cells contribute to the dampening of innate and adaptive immune responses during acute viral infection, we addressed the frequency and number of CD4+CD25+Foxp3+ Treg cells in the spleen." (PMID 25188232, 2014). "They suggested that IL-1β may enhance IgM antibody responses and the recruitment of CD4+ T cells to viral infection sites." (PMID 24676272, 2014). "Thus, Paneth cells play a critical role in the induction of gut inflammation during the early stages of viral infection, prior to the depletion of CD4+ T cells." (PMID 25166758, 2014). "In addition to modulation of the conventional population of CD8+ and CD4+ T cells, Mtv have been demonstrated to influence the immune system during viral infection via expansion of a particular subset of CD4+ T cells expressing the transcription factor Foxp3." (PMID 24324930, 2013). "Recently, a rhesus CMV-vectored SIV vaccine was shown to induce potent and durable SIV-specific CD8+ and CD4+ T cell responses that conferred long-term protection against systemic viral infection and CD4+ cell depletion in over half of the vaccinated animals that were challenged with pathogenic SIV." (PMID 23866844, 2013).